IDO1 (indoleamine 2,3-dioxygenase 1)
Description:
Catalyzes the first and rate limiting step of the catabolism of the essential amino acid tryptophan along the kynurenine pathway. Involved in the peripheral immune tolerance, contributing to maintain homeostasis by preventing autoimmunity or immunopathology that would result from uncontrolled and overreacting immune responses. Tryptophan shortage inhibits T lymphocytes division and accumulation of tryptophan catabolites induces T-cell apoptosis and differentiation of regulatory T-cells. Acts as a suppressor of anti-tumor immunity. Limits the growth of intracellular pathogens by depriving tryptophan. Protects the fetus from maternal immune rejection.
Synonyms: IDO-1; IDO; INDO
Tractability: Small molecule: a drug acting on it is in phase 2 or 3 trials; a structure with a bound ligand is known; a high-quality ligand is known; it has a high-quality binding pocket; it belongs to a druggable protein family. PROTAC: it is named in the literature on targeted protein degradation; a small molecule that binds it is known.
Target class: Enzyme; Oxidoreductase
Chemical probes: GNF-PF-3777, IDO5L, MMG-0358, PD134496, PD134497
Safety:
Unwanted effects reported when the protein is acted on. In parentheses: how it was acted on, where the effect was seen, and who reports it.
moderate or severe depression (source: ClinPGx)
Gene: Protein-coding gene on chromosome 8 (39,902,275 to 39,928,790, forward strand). Ensembl gene ENSG00000131203.
Subcellular location: Cytoplasm, cytosol
Subcellular location (Human Protein Atlas): Microtubules; Basal body; Cytokinetic bridge; Mitotic spindle; Primary cilium
Pathways (Reactome):
Metabolism: Tryptophan catabolism
Gene Ontology:
Molecular function: indoleamine 2,3-dioxygenase activity; L-tryptophan 2,3-dioxygenase activity; electron transfer activity; heme binding; metal ion binding
Biological process: positive regulation of T cell apoptotic process; regulation of activated T cell proliferation; 'de novo' NAD+ biosynthetic process from L-tryptophan; female pregnancy; L-tryptophan catabolic process; quinolinate biosynthetic process
Cellular component: cytoplasm; cytosol; smooth muscle contractile fiber; stereocilium bundle
Genetic constraint (gnomAD): Loss-of-function variants: 15 observed, 18.67 expected, observed/expected ratio (o/e) 0.8, 90% interval 0.54 to 1.24. The upper end of that interval is the gene's LOEUF score, 1.24, which puts it in group 5 of 6, group 1 being the genes least tolerant of losing a copy. Missense variants: 391 observed, 367.76 expected, observed/expected ratio (o/e) 1.06, 90% interval 0.98 to 1.16. Synonymous variants: 129 observed, 140.21 expected, observed/expected ratio (o/e) 0.92, 90% interval 0.8 to 1.07.
Homologues: Orthologues: chimpanzee IDO1 (99% identical), macaque IDO1 (94% identical), pig IDO1 (73% identical), rabbit IDO1 (72% identical), dog IDO1 (67% identical), guinea pig IDO1 (65% identical), rat Ido1 (62% identical), mouse Ido1 (62% identical).
Diseases named in the same sentence as IDO1 in open-access papers:
IDO1 is named in the same sentence as 521 diseases in open-access papers, as found by Europe PMC text mining. Sharing a sentence is not in itself a finding about the gene and the disease. The quoted sentences say what the papers report.
melanoma (282 papers, 2009 to 2026). A malignant, usually aggressive tumor composed of atypical, neoplastic melanocytes. "Prolonged exposure of melanoma cells to IFN-γ was associated with IDO1-mediated depletion of tryptophan followed by the bypass of tryptophan codons by ribosomes in the absence of tryptophan." (PMID 40108693, 2025). "Prior research suggested that a reduced Trp/Kyn ratio is linked to lower survival rates in melanoma patients, particularly among cases where IDO-1 upregulation was present." (PMID 39062529, 2024). "IDO1 associates with adverse clinical outcome in melanoma patients, and its activity promotes an immunosuppressive TME by upregulating trafficking of MDSCs and Tregs." (PMID 36389735, 2022). "In melanoma patients, high levels of IDO1 are associated with high levels of Kyn and immunosuppression." (PMID 36588678, 2022). "In a B16 melanoma model, the IDO1 inhibitor LW106 decreased tumor-associated stromal cells and COL deposition, and increased infiltration of effector cells." (PMID 34177968, 2021). "Combining agonistic CD40 mAb therapy with the IDO1 inhibitor epacadostat delayed tumor growth in B16-F10 melanoma, associated with increased activation of tumor-infiltrating T-cells." (PMID 32231867, 2020). "Mechanically, accumulating studies have implicated IDO1 expression on pDCs was necessary to confer suppressive function to Tregs in many diseases such as melanoma, experimental autoimmune encephalomyelitis (EAE), rheumatoid arthritis and atherosclerosis." (PMID 32076400, 2020). "High IDO1 in sentinel lymph nodes has demonstrated to be associated with a reduction in TILs and worse prognosis in melanoma patients." (PMID 32575899, 2020). "In the current study, we investigate the prognostic role of PARP1, PD-L1, and IDO1 protein expression and explore the possible associations between tumoral PARP1, PD-L1, and IDO1 expression in a series of mucosal melanomas." (PMID 32380691, 2020). "Further, high expression of IDO1 may be associated with resistance to PD-1 inhibition in non–small cell lung cancer, melanoma, and RCC." (PMID 39054430, 2024). "Indoleamine-2,3-dioxygenase (IDO1) pathway has vital role in cancer immune escape and its upregulation leads to immunosuppressive environment which is associated with poor prognosis and progression in various cancers like melanoma." (PMID 37037839, 2023). "Of greater relevance to the cancer therapy field, is that clear associations between high IDO1 expression and poor patient outcome have been documented for many difficult-to-treat cancers that include glioma, melanoma, prostate, endometrial, ovarian, breast, pancreatic, lung, and colorectal cancers." (PMID 36145311, 2022). "Clinical studies have suggested IDO-1 activity could be associated with various cancers including melanoma, colorectal, breast, lung, and brain cancers." (PMID 33330446, 2020). "IDO1 expression by tumor cells has been associated with significantly worse clinical prognosis and reduced survival in malignant melanoma, pancreatic cancer, ovarian cancer, both pediatric and adult acute myelogenous leukemia, colorectal cancer, prostate cancer, endometrial cancer, and others." (PMID 32637034, 2020). "In contrast, pro-tumoral effects of IFNγ have been observed in colon carcinoma and melanoma, leading to a loss of IFNγ signaling sensitivity, reduced antigen expression, and induction of key immune suppressive molecules such as indoleamine-2,3-dioxygenase (IDO1) and immune checkpoint proteins." (PMID 35003017, 2021). "Downregulation of VISTA, IDO1 and ICOS was associated with melanomas that gave rise to distant metastases including brain." (PMID 40621453, 2025). "This association parallels the failure of IDO inhibitor trials in melanoma, prompting us to investigate the prognostic impact of IDO1 expression across pan-cancer datasets." (PMID 40427178, 2025).
melanoma (continued). "Phase III clinical trial of IDO1 inhibitor epacadostat in combination with PD-1 checkpoint inhibitor pembrolizumab for melanoma declared a failure in 2018 (Ref." (PMID 40040508, 2025). "In two humanized mouse models for melanoma and lymphoma with added MSCs, IDO1 inhibited the proliferation of CD8(+) T cells and B cells and promoted tumor growth." (PMID 40699630, 2025). "Like IL6/STAT3, genetic and pharmacological targeting of GLI1 showed that IFNγ/STAT1 requires functional GLI as a second signal for the full-blown induction of IDO1 in human melanoma cells." (PMID 39962447, 2025). "The correlation between IDO1 and CXCL9 (as an IFN-γ responsive marker) has been assessed in colorectal carcinomas, melanomas, and other cancer types, but the correlation between IDO and IL-10RA in real tumours remains poorly elucidated." (PMID 39592739, 2025). "Although IDO1 is abundantly expressed in melanoma tissue, and IFN-γ-elicited over-expression of IDO1 reduces Trp and increases Kyn concentrations in in vitro skin models, the concentrations of Trp and Kyn in melanoma tissue remain to be assessed." (PMID 40554511, 2025). "A recent study suggested that IDO1 also acts as a signaling molecule, promoting malignant progression in melanoma, offering new therapeutic insights." (PMID 41332472, 2025). "• Tryptophan Catabolism—A Minor Pathway in OS?: The indoleamine 2,3-dioxygenase 1 (IDO1)–kynurenine–AhR axis is a dominant immunosuppressive pathway in many cancers such as melanoma." (PMID 41209019, 2025). "Accumulation of IDO-1-positive dendritic cells (DCs) was found in draining nodes from patients with melanoma, breast, colon, lung, pancreatic cancers and hepatocarcinoma." (PMID 40475772, 2025). "IFNγ/STAT1 signaling is known to be both a crucial player in anti-tumoral immune responses as well as a strong activator of immunosuppressive IDO1 expression, particularly in melanoma." (PMID 39962447, 2025). "Strikingly, IDO1, along with other kynurenine pathway genes previously targeted in melanoma (IDO2 and TDO2), also correlated with better outcomes in SKCM.met." (PMID 40427178, 2025). "Kynurenine: Generated from tryptophan metabolism by enzymes like indoleamine 2,3-dioxygenase 1 (IDO1), which is often upregulated in melanoma." (PMID 41346595, 2025). "In line with our observations of IL6-treated cells, genetic inhibition of GLI1 expression strongly reduced IFNγ-mediated transcriptional induction of IDO1 in WM35 melanoma cells as measured by qPCR." (PMID 39962447, 2025). "Further, IDO1 activation in melanoma has been demonstrated to recruit myeloid derived suppressor cells (MDSCs) via enhancing Treg numbers, thereby contributing to immune evasion and resistance to immunotherapy." (PMID 39962447, 2025). "IFN-γ can regulate the kynurenine pathway, which is activated by indoleamine 2,3-dioxygenase 1 (IDO1) to catabolize tryptophan into kynurenine and exert immunosuppressive effects in both melanoma and normal cells in the skin." (PMID 40108693, 2025). "By contrast, conditioned media from IFNγ-treated melanoma cells, which exhibited high levels of kynurenine due to strong IDO1 expression, profoundly inhibited the proliferation of CD4+ as well as CD8+ T cells." (PMID 39962447, 2025). "The combination of anti-CTLA-4 monotherapy with an IDO1 inhibitor resulted in melanoma tumor regression and was dependent on the activity of CD8 + T-cells and IFN-γ." (PMID 40108693, 2025). "We conducted a proteome analysis of DC2s in tumor-free conditions compared to DC2s cultured with melanoma-secreted factors, revealing increased IDO1 and LGMN in ti-DC3s." (PMID 40789452, 2025). "In melanoma, increased expression of IDO1 or tryptophan 2,3-dioxygenase (TDO), another enzyme involved in metabolizing tryptophan to AhR ligands, increases the abundance of TAMs and polarizes to a more M2-like immunosuppressive phenotype." (PMID 38339226, 2024).
melanoma (continued). "Increased Trp catabolism to Kyn was observed in IFN-γ-stimulated melanoma and melanocyte models, along with higher IDO-1 expression." (PMID 39062529, 2024). "In this study, the authors demonstrated that restoring tryptophan with IDO1 inhibitors in a TRP-deprived milieu protected melanoma cells from being eliminated by T cells by recovering general protein synthesis triggered by IFNγ-induced tryptophan deprivation." (PMID 38273337, 2024). "Immunotherapies, including immune checkpoint inhibitors (such as anti-PD-1 and anti-IDO1 antibodies and adoptive cell therapy, aim to activate and enhance the body's immune response against melanoma cells." (PMID 38188364, 2024). "Of note, experimental data suggest that BRAF inhibitor treatment can reduce IDO1 expression, while high IDO1 levels can be detected in melanoma samples in connection with the development of resistance to the BRAF inhibitor." (PMID 39272837, 2024). "A study of advanced melanoma revealed that only 39.5% of patients had tumors with elevated IDO expression, and only 9.3% expressed both IDO1 and PDL1." (PMID 38339226, 2024). "Administering the IDO1 inhibitor, LW106, to melanoma cells resulted in a reduction in tumor-associated stromal cells and collagen deposition, consequently eliciting CTL infiltration." (PMID 39107856, 2024). "The range of melanomas featuring upregulated IDO-1 expression spans from approximately 15–92%, with ongoing research aimed at refining these statistics." (PMID 39062529, 2024). "CD40 mAb combined with epacadostat, an IDO1 inhibitor, reduced tumor growth in B16-F10 melanoma, accompanied by an increase in tumor-infiltrating T cells." (PMID 38539263, 2024). "Similar induction of IDO1 also appears to occur in patients, as indicated by the elevation of systemic kynurenine-to-tryptophan ratios in α-PD-1-treated sarcoma, melanoma and renal cell carcinoma patients." (PMID 39211039, 2024). "For example, higher IDO1 expression correlated with better survival in melanoma patients, whereas high IDO1 expression predicted poorer survival in patients with glioblastoma when compared with patients with low IDO1 expression." (PMID 38736462, 2024). "Immunosuppression arises when the overexpression of IDO-1 in the skin depletes Trp and generates excessive amounts of Kyn, which decreases the Trp/Kyn ratio in the melanoma TME." (PMID 39062529, 2024). "The staining revealed that following IFN-γ stimulation, noticeable localization of IDO-1 was present in both fibroblasts and some melanoma cells in the melanoma nests, relative to the control." (PMID 39062529, 2024). "The therapeutic efficacy of regorafenib in melanoma has also been suggested due to its role in attenuating INFγ-induced PD-L1 and IDO1 expression." (PMID 39273017, 2024). "Immunomodulatory CAFs (iCAFs) displayed high expression of MMP1, MMP3, IL6, CXCL8, and IDO1, and included CAFs from melanomas, 1 SCC, and 1 BCC." (PMID 38525245, 2024). "IDO-1 expression in primary human melanoma has been shown to significantly correlate with Breslow index describing the thickness of the melanoma, the presence of tumour infiltrating lymphocytes, and the intensity of the inflammatory infiltrate." (PMID 38188364, 2024). "In preclinical models, anti–PD-1 treatment combined with an IDO1 inhibitor showed synergistic antitumor activity in models of melanoma and glioblastoma." (PMID 39054430, 2024). "To extend this model we have investigated cell viability, mRNA levels of IDO-1, PD-L1, and the Kyn/Trp ratios in six different human melanoma cell lines as well as in primary adult melanocytes after exposure to IFN-γ." (PMID 38188364, 2024). "In B16 melanoma cells, the ectopic apo-IDO1 protein has a greater stability compared to the holo-IDO1 protein." (PMID 38333210, 2024). "Cell function assay showed that IDO1 was significantly overexpressed in the melanoma A375 cell line." (PMID 37305390, 2023).
melanoma (continued). "For instance, melanoma cells highly express indoleamine-pyrrole 2,3-dioxygenase (IDO1) and prostaglandin E2 (PGE2), both of which have immunosuppressive activity." (PMID 38067178, 2023). "This value is quite similar to the one described in the literature for mouse IDO1 overexpressed in B16F10 melanoma (88 nM), but higher than the one measured with the human protein (10 nM)." (PMID 37122718, 2023). "Increased expression of IDO1 is observed in many tumors, including colorectal, hepatocellular, ovarian, and melanomas." (PMID 37817770, 2023). "Higher plasma IDO1 activity has been documented in lung, gynaecological, breast, colorectal and melanoma malignancies, and upregulated expression of IDO in the microenvironment of laryngeal and oesophageal carcinomas." (PMID 37644823, 2023). "Indoximob, another IDO-1 inhibitor was recently evaluated in combination with ICB in a phase II clinical trial on melanoma patients." (PMID 37180110, 2023). "First, PCR results showed that IDO1 expression was upregulated in melanoma A375 cell lines and WM-115 cell lines compared with normal epidermal HaCaT cell lines (*p < 0.05)." (PMID 37305390, 2023). "A previous phase III clinical trial in advanced melanoma examined the clinical benefit of combining an IDO1 inhibitor (epacadostat) with a PD‐1 inhibitor (pembrolizumab); the results indicated that patients failed to benefit significantly from the treatment." (PMID 37148546, 2023). "We then queried if the enhanced IDO1 inhibition of Epacasome-2 would lead to better reversion of T-cell suppression mediated by IDO1-expressing B16–F10 melanoma cells." (PMID 37945606, 2023). "Cell function experiments were performed to validate the role of the IDO1 gene in melanoma cell line A375." (PMID 37305390, 2023). "Previous studies also report that endothelial cells are able to express IDO1 in different malignancies, e.g., melanoma and carcinomas (e.g., cervix and lung)." (PMID 36830609, 2023). "In contrast to IDO1, which showed inducible expression, both melanoma cell lines exhibited high basal levels of COX-2 expression." (PMID 37444608, 2023). "discover an adverse effect of IDO1 inhibition: protecting melanoma cells from the effects of T cell-derived IFNγ." (PMID 36812891, 2023). "We show here that IDO1 inhibition leads to an adverse protection of melanoma cells to T cell-derived interferon-gamma (IFNγ)." (PMID 36812891, 2023). "Previously, macrophages were observed to be the predominant source of IDO1 expression in brain metastases of melanoma." (PMID 35963900, 2023). "Epacadostat, an IDO1 inhibitor, has been evaluated in combination with pembrolizumab in patients with advanced melanoma in a Phase III, randomized, clinical trial." (PMID 35565190, 2022). "B16F10 melanoma cells expressing constitutively IDO1 were shown to inhibit the proliferation and induce the apoptosis of naive co-cultured T cells." (PMID 36188218, 2022). "In patients with melanoma, IDO1 expression were first observed in a subset of cells with plasmacytoid shape in SLN." (PMID 35408802, 2022). "Consistently, the transcriptomic analysis reported a strong correlation between CD8+ T-cell infiltration and IDO1 expression in tumor models, such as melanoma." (PMID 36119020, 2022). "In melanoma, IDO1 expression was found to be increased in different stages of melanoma development, progression, and BRAF inhibitors resistance." (PMID 35742834, 2022). "In line with this in vitro analysis, B16F10 transplantable melanomas grew more slowly in mice treated with IDO1 inhibitors or IDO1-siRNA injected intratumorally, than in control mice." (PMID 36188218, 2022). "Metabolic modulators are relatively new to melanoma treatment and so far have included IDO1 inhibitors and HDAC inhibitors in phase 3 trials." (PMID 36358601, 2022). "In this study, we investigated the expression of the tolerogenic enzyme IDO1 by LCs in SLN of patients with melanoma in order to understand their role in tolerance towards melanoma." (PMID 35408802, 2022).